CCR6 (C-C motif chemokine receptor 6)
Diseases named in the same sentence as CCR6 in open-access papers (continued):
Sharing a sentence is not in itself a finding about the gene and the disease.
atherosclerosis (continued). "Fourth, CCL18 administration in hyperlipidemic CCR6−/− mice neither did aggravate atherosclerosis nor did induce T-cell accumulation in plaque, unlike WT mice that rendered hyperlipidemic by PCSK9 gene transfer." (PMID 38807599, 2024). "It signals via the Ccr6 receptor and the importance of the CCL20/Ccr6 axis for development of atherosclerosis was demonstrated in ApoE−/− mice lacking Ccr6, which had reduced size of the atherosclerotic lesions." (PMID 38350853, 2024). "CCR6 and its ligand CCL20 have emerged as important regulators of atherosclerosis." (PMID 33679793, 2021). "Moreover, the bulk of CCR6 staining colocalized with CD3+ T cells, and a tight correlation was observed between plaque CCL18 and CCR6 expression at mRNA level, lending further support to a link between CCR6 and CCL18 in atherosclerosis." (PMID 38807599, 2024).
lymphoma (7 papers, 2009 to 2025). A malignant (clonal) proliferation of B- lymphocytes or T- lymphocytes which involves the lymph nodes, bone marrow and/or extranodal sites. "Although CCR3, CCR6, CCR8, PITPNM3, and GPER1 encode receptors of CCL18, only CCR6 was expressed in the lymphoma cells." (PMID 39894788, 2025). "Lymphoma patients showed increased numbers of cTfh1 and reduced cTfh17 cells due to decreased expression of the subset-defining marker CCR6 in patients." (PMID 29293620, 2018). "Unexpectedly within the CD4+CXCR5+CCR6+ population there were significant reductions in CCR6 expression in lymphoma patients as compared to normal subjects." (PMID 29293620, 2018). "Additionally, a moderate expression of CCR6 was found on the majority of lymphoma cell surfaces in both of the molecular subtypes." (PMID 35887224, 2022). "On the other hand, overexpression of CCR6 in lymphoma cells might possibly drive tumor growth through CCL20-mediated recruitment of tumor-associated macrophages." (PMID 33288848, 2020). "RNA sequencing revealed upregulated expression of chemokine genes, including CCL5, CCL18, and CCL19, in WDL and that of the corresponding chemokine receptor genes CCR4, CCR6, and CCR7 in the lymphoma cells." (PMID 39894788, 2025). "The expression of chemokine receptors, CCR4 for CCL5, CCR6 for CCL18, and CCR7 for CCL19, was upregulated in lymph nodes with conspicuous lymphoma infiltration, likely representing their expression in lymphoma cells." (PMID 39894788, 2025). "Upregulated expression of CCR4 for CCL5, CCR6 for CCL18, and CCR7 for CCL19 was observed in lymph nodes, where lymphocytes were replaced by lymphoma cells." (PMID 39894788, 2025). "Our immunohistochemical analysis demonstrated moderate to strong expression of CCR5, CCR6, and CCR8 on the surface of the lymphoma cells in all of the investigated subgroups." (PMID 35887224, 2022). "A similar analysis on CD4+CXCR5+CCR6+ (cTfh1/17 and cTfh17) populations also confirms increased PD1 expression in lymphoma patients." (PMID 29293620, 2018). "Next we compared global changes in CXCR3, CCR6 and PD1 expression between normal subjects and patients with lymphoma." (PMID 29293620, 2018). "Furthermore, the continuous upregulation of CCR6 was discovered, which results in the continuous activation of CCR6-CCL20, leading the lymphoma cells to metastasize to internal organs." (PMID 34948183, 2021).
psoriatic arthritis (7 papers, 2019 to 2023). Joint inflammation associated with psoriasis. "Alterations in CCR6+ ILC have also been reported in psoriatic arthritis, with diminished CCR6+ ILC in peripheral blood but enhanced numbers in synovial fluid." (PMID 36578284, 2022). "Given the higher efficacy of anti-IL-17A in psoriatic arthritis, it would be of great interest to study differences in the induction of the pro-inflammatory feedforward loop by the CCR6+ memTh subpopulations between RA and PsA patients in future studies." (PMID 34082814, 2021). "Also, CCR6 has been shown to have an important impact on the pathogenesis of psoriatic arthritis (PsA), and targeting CCR6 could have a promising effect in the treatment of PsA." (PMID 38156398, 2023). "In subjects with psoriatic arthritis, increased levels of CD8+ CCR6+ T-cell effectors expressing CD69 were found in peripheral blood, and the accumulation of CXCR3+ CD8+ and CD69+T cells was also revealed in the synovial fluid of inflamed joints." (PMID 37892710, 2023). "In the circulation, we found increased percentage of CD8+ CCR6+ T cell effectors expressing CD69 and of IL-17-producing T cells in patients with psoriatic arthritis." (PMID 31350460, 2019).
type 1 diabetes (7 papers, 2015 to 2025). "This study suggests that inhibition of those cells’ CCR6+ migration may provide an approach for treating type 1 diabetes." (PMID 37092451, 2023). "Similarly, an effector memory Treg subset expressing HLA-DR, CCR4, CCR6, CXCR3, and GATA3 was increased in the high-risk group of patients with type 1 diabetes." (PMID 37189479, 2023). "In a study with a NOD model mouse of type 1 diabetes treated with resveratrol to prevent and treat type 1 diabetes, it was discovered that the expression of CCR6 decreased and the presence of CCR6+ IL-17 producing cells decreased in the pancreas after treatment." (PMID 37092451, 2023).
non-small cell lung carcinoma (6 papers, 2013 to 2023). A group of at least three distinct histological types of lung cancer, including non-small cell squamous cell carcinoma, adenocarcinoma, and large cell carcinoma. "The CCL20/CCR6 axis has been shown to promote non-small cell lung cancer progression." (PMID 23800251, 2013).
renal cell carcinoma (6 papers, 2014 to 2022). "TAMs are involved in tumor cell migration through the activated AKT signaling pathway via the CCL20/CCR6 axis in renal cell carcinoma." (PMID 35841069, 2022). "In 42 renal cell carcinoma tissues, patients with CCR6 and macrophage infiltration indicated poor prognoses." (PMID 31905918, 2019).
thyroid cancer (6 papers, 2018 to 2025). "CCR6 has been found to be significantly upregulated in thyroid cancer cells compared to normal thyroid epithelial cells." (PMID 40150133, 2025). "For example, the CCL20/CCR6 interaction enhanced the invasion and migration properties of thyroid cancer cells by activating NF-κB and inducing the expression and secretion of MMP-3." (PMID 36380313, 2022). "In an animal model, the chemokine receptor CCR6 was upregulated in small liver metastases of thyroid carcinoma, highlighting its putative rule in early detection of pediatric liver metastasis." (PMID 33915699, 2021). "Its receptor (CCR6) was also found to be highly expressed in thyroid cancer cells." (PMID 29977225, 2018). "In thyroid cancer, CCL20/CCR6 promotes the invasion and migration of thyroid tumor cells via p65 NF-κB signaling." (PMID 30052635, 2018). "The specificity of this CCL20–CCR6 interaction was demonstrated by the fact that CCR6 knockdown inhibits the CCL20-induced invasiveness and migration of thyroid cancer cells." (PMID 29977225, 2018).
breast tumor (5 papers, 2011 to 2023). "PITPNM3 has been proven to be a functional CCL18 receptor in breast tumor cells and T lymphocytes, while CCR6 and CCR8 have been proven to be expressed in T lymphocytes." (PMID 36418470, 2023). "We also found higher CCR6 expression in Black versus White patients with luminal A molecular subtype breast tumors." (PMID 35754051, 2022). "In breast tumour, just like its counterpart in the blood, the CCR6 defines an IL17A producer and the CD16 subtype is an IFNγ producer with high cytotoxic potential." (PMID 33268347, 2021). "CCR3 and CX3CR1 were differentially expressed between Black versus White, and CCR6, CCRL2, and CXCR4 between Asian versus White breast tumors." (PMID 35754051, 2022). "CCR4 is known to be down regulated on Tregs after their sensitization to CCL22 but other chemokine receptors, such as CCR6, which are expressed on these Tregs, which is interaction with CCL20 production by breast tumor cells." (PMID 24124553, 2013).
dermatitis (5 papers, 2012 to 2024). An inflammatory process affecting the skin. "Given the critical role for both DCs and CCR6 in the IL-23-induced skin inflammation, and the expression of CCR6 on various DC subsets, we investigated a possible role for CCR6 on DCs in this model." (PMID 27982014, 2016). "Taken together, our data suggest that one role for CCR6 in IL-23-induced skin inflammation is the recruitment of blood monocytes that serve as precursors for moDCs." (PMID 27982014, 2016). "Comparison of CCR6 KO and WT mice confirmed that CCR6 expression was required for IL-23-induced dermatitis." (PMID 22229105, 2012). "However, using mice transplanted with a mixture of bone marrows from Ccr6−/− and CD11c-DTR mice, we established that CCR6 was necessary on DCs and/or their precursors for the IL-23-induced skin inflammation." (PMID 27982014, 2016). "IL-23-induced skin inflammation was virtually eliminated in DT-treated CD11c-DTR mice, Ccr6−/− mice and mice transplanted with a mixture of Ccr6−/− and CD11c-DTR bone marrow and treated with DT." (PMID 27982014, 2016). "However, following the treatment with DT, mice that received the mixture of Ccr6−/− and CD11c-DTR bone marrow cells were protected from IL-23-induced skin inflammation." (PMID 27982014, 2016).
glomerulonephritis (5 papers, 2013 to 2018). A renal disorder characterized by damage in the glomeruli. "It has also been demonstrated that pathogenic Th17 cells expressing CCR6 play a key role in accelerating organ injury in animal models of glomerulonephritis and arthritis." (PMID 29441231, 2018). "Moreover, the chemokine receptor, CCR6, expressed on Th cells, has been implicated in mediating the recruitment of IL-17 producing cells in glomerulonephritis." (PMID 29441231, 2018). "Th17 cells highly express CCR6, which orchestrates their trafficking to the small intestine but also to sites of peripheral inflammation, such as the kidney in glomerulonephritis." (PMID 27851911, 2016). "This is in line with a recent study demonstrating that the CCL20/CCR6 axis also mediates renal recruitment of Tregs, and that the reduction of anti-inflammatory Tregs in the presence of a fully functional Th1 response aggravates experimental glomerulonephritis." (PMID 27851911, 2016). "We utilized photoconversion of intestinal cells in Kaede mice to track intestinal T cell mobilization upon glomerulonephritis induction, and we found that Th17 cells egress from the gut in a S1P-receptor-1-dependent fashion and subsequently migrate to the kidney via the CCL20/CCR6 axis." (PMID 27851911, 2016).
laryngeal carcinoma (5 papers, 2019 to 2023). Carcinoma that arises from the laryngeal epithelium. "Another study showed that compared to normal tissues or cells, CCR6 was overexpressed in laryngeal cancer tissues or cell lines." (PMID 36447119, 2023). "The correct reference is “Lu, E.; Su, J.; Zhou, Y.; Zhang, C.; Wang, Y. CCL20/CCR6 promotes cell proliferation and metastasis in laryngeal cancer by activating p38 pathway." (PMID 31146450, 2019). "Reference 92 to “Lu, E.; Su, J.; Zhou, Y.; Zhang, C.; Wang, Y. CCL20/CCR6 promotes cell proliferation and metastasis in laryngeal cancer by activating p38 pathway." (PMID 31146450, 2019). "In addition, CCL20/CCR6 promotes cell proliferation and metastasis in laryngeal cancer by activating the p38 pathway." (PMID 31395078, 2019).
liver cancer (5 papers, 2022 to 2024). An epithelial or non-epithelial malignant neoplasm that arises from the liver. "In line with our observations, the CCL20/CCR6 axis has been directly linked to promote carcinogenesis in several cancer entities including primary liver cancers by re-shaping the immunologic TME and subsequently migration as well as proliferation of cancer cells." (PMID 36982370, 2023). "Myeloid malignancies with elevated IL1RAP and CCR6+ cancers that respond to CCL20 such as liver cancer might be first candidates." (PMID 36107259, 2022). "Gene expression analysis in liver cancer cell lines (HePG2) revealed that M levan decreased the expression of CCL20), 2GRB2, and CCR6) genes and was superior to Doxo." (PMID 38326332, 2024). "Where, its mode of action was explained by liver cancer-related genes such as CCL20, GRB2, and CCR6 as well as immune-related genes IL4R and IL10, and a possible correlation between the levan in lowering the anti-migratory activity and its cytotoxicity effect in HepG2." (PMID 38326332, 2024).
liver disease (5 papers, 2011 to 2023). "We have now assessed the expression and the role of CCR6 in the context of liver injury to understand the weight of CCR6-dependent recruitment of inflammatory cells in liver disease." (PMID 26691857, 2015). "Defining the role of chemokines and chemokine-receptors such as CCL20 and CCR6 in liver injury is of paramount importance to better understand liver disease and to develop new targeted therapeutic strategies." (PMID 26691857, 2015). "Although the role of CCR6 in liver diseases is not clear, the association between CCR6 hepatic expression and cirrhosis and its correlation with clinical scores of disease severity has been shown." (PMID 37092451, 2023). "Understanding the chemokines and chemokine receptors promoting hepatic Th17 cell recruitment (possibly CCR6 or CCR4) might reveal new therapeutic targets interfering with Th17 migration or differentiation in liver disease." (PMID 21197451, 2011). "This study, together with previous data investigating the role of CCL20 in liver disease, identifies the CCL20/CCR6 pathway as an important player in liver disease." (PMID 26691857, 2015). "Finally, increased CCR6 hepatic expression in patients with alcoholic hepatitis was found to correlate with liver expression of CCL20 and severity of liver disease." (PMID 26691857, 2015). "Human liver-infiltrating Th17 expressed high levels of chemokine receptors, CCR6 68 ± 11% (mean ± SD), CXCR3 47 ± 11%, and CCR4 44 ± 13%, irrespective of the cause of liver disease." (PMID 22796894, 2012).
liver fibrosis (5 papers, 2012 to 2024). "Notably, the number of CCR6+ cells correlated positively with both inflammation severity (r = 0.682, P < 0.001) and hepatic fibrosis stage (r = 0.515, P = 0.005) in PBC." (PMID 38405661, 2024). "Moreover, adoptively transferred Ly6Chi monocytes traffic into the injured liver and promote fibrosis progression in wildtype and CCR2-/-CCR6-/- mice, which are otherwise protected from hepatic fibrosis." (PMID 23259611, 2012). "We therefore performed immunofluorescent staining using CCR6 as marker for IL-17A–producing CD4+ T cells, and α-smooth muscle actin (αSMA) as marker for the cells potentially responsible for liver fibrosis." (PMID 36625344, 2023). "Impaired monocyte subset recruitment in CCR2-/- and CCR2-/-CCR6-/- mice resulted in reduced HSC activation and diminished liver fibrosis." (PMID 23259611, 2012).
lung adenocarcinoma (5 papers, 2011 to 2025). A carcinoma that arises from the lung and is characterized by the presence of malignant glandular epithelial cells. "The modification of CAR-T cells targeting the lung adenocarcinoma antigen MUC1 for the chemokine receptor CCR6 enhanced migration toward tumor sites rich in CCL20 and CAR-T cell efficacy." (PMID 41181132, 2025). "To examine the correlation between CCR6 expression and NSCLC disease stage, we measured CCR6 staining index in a tumor tissue array enclosing lung adenocarcinoma samples homogenously spread among the different disease stages." (PMID 21949768, 2011). "Using Kaplan-Meier analysis, we looked for associations between the clinical course of lung adenocarcinoma patients and the extent of CCL20/CCR6 staining in their tumor samples." (PMID 21949768, 2011). "Using immunohistochemistry, we defined the expression patterns of CCL20 and CCR6 in lung adenocarcinoma." (PMID 21949768, 2011). "CCL20/CCR6 interactions can lead to proliferation and migration dependent in part on extracellular signal-regulated kinase (ERK) phosphorylation during lung adenocarcinoma growth." (PMID 29788995, 2018). "Immunohistochemistry studies indicated that the majority of lung adenocarcinoma tumor samples highly stained for CCL20, while only a minority highly expressed CCR6." (PMID 21949768, 2011). "To study the clinical relevance of CCL20/CCR6 expression in NSCLC, we tested the expression of the chemokine and receptor in 49 lung adenocarcinoma tissue samples removed during surgery." (PMID 21949768, 2011).
lupus nephritis (5 papers, 2010 to 2023). Glomerulonephritis in the context of systemic lupus erythematosus. "Further investigation is needed to clarify the association of Fli-1 in CCL20 expression and infiltration of CCR6+ Th17 cells in lupus nephritis." (PMID 32183259, 2020). "Patients with lupus nephritis showed significantly higher levels of CD80 expression on CD4+CCR6+ cells in comparison to healthy controls (22.13 ± 10.58% vs. 18.86 ± 3.82%, P = 0.02)." (PMID 20653937, 2010). "Chemokines and chemokine receptors are used as therapeutic targets in lupus nephritis; therefore, we assessed the surface expression of the most important chemokine receptors (CCR6, CCR7, CXCR4 and CXCR5) on B lymphocytes from all four groups by flow cytometry." (PMID 25909640, 2015). "Patients with and without active disease, as assessed by SLEDAI, and patients with and without lupus nephritis, proven by renal biopsy, were analysed for CD80 expression on CD4+CCR6+ cells." (PMID 20653937, 2010).
systemic sclerosis (5 papers, 2015 to 2021). A chronic disorder, possibly autoimmune, marked by excessive production of collagen which results in hardening and thickening of body tissues. "IL-17A-producing T cells are characteristically increased in peripheral blood of patients with systemic sclerosis (SSc) and they are characterized by expression of chemokine receptor CCR6 responsible for with skin- and lung-homing capabilities." (PMID 26062902, 2015).
allergic asthma (4 papers, 2021 to 2024). A asthma with a basis in a pathological type I hypersensitivity reaction. "In this study, we demonstrated that the pathogenesis of allergic asthma may be associated with CCR6+ Treg cells recruitment." (PMID 34497608, 2021). "Treg cells expressing CCR6 have the potential to promote inflammation and exacerbate allergic asthma." (PMID 37795866, 2023). "We found the proportions of CCR6+IL-17+ and CCR6+ICOS+ Treg cells were both lower in patients with allergic asthma than in healthy subjects." (PMID 34497608, 2021). "Moreover, the relative contribution of CCR6+ Treg cells to the pathogenesis of allergic asthma is likewise unclear." (PMID 34497608, 2021). "Human allergic asthma constitutes an inflammatory microenvironment enriched with chemokines, such as CCL20, which promotes the migration of circulating CCR6+ Treg cells." (PMID 34497608, 2021). "The CCR6+IL-17+ Treg cells subsets and the CCR6+ICOS+ Treg cells subsets decreased significantly in patients with allergic asthma compared with HC." (PMID 34497608, 2021).
cutaneous T-cell lymphoma (4 papers, 2016 to 2022). "A second study on cutaneous T cell lymphoma documented inhibition of CCR6 by micro RNA-150 (MiR-150) leading to strong downregulation of tumor metastasis." (PMID 30453514, 2018). "In cutaneous T-cell lymphoma, upregulation of miR-150 inhibited tumor invasion and metastasis by targeting the chemokine CCL20 receptor, CCR6." (PMID 29069826, 2017). "We recently demonstrated that upregulation of a chemokine receptor CCR6 and its ligand CCL20 led to metastasis of advanced cutaneous T-cell lymphoma (CTCL) cells, suggesting the involvement of CCL20-CCR6 interaction in initiating CTCL cell metastasis." (PMID 26789110, 2016).
diabetes (4 papers, 2018 to 2025). "Several studies based on preclinical and translational data predict the involvement of the CCL20/CCR6 axis in the development of diabetes and DKD, the leading cause of CKD." (PMID 41226600, 2025).